IMP3 (IMP U3 small nucleolar ribonucleoprotein 3)
Diseases named in the same sentence as IMP3 in open-access papers (continued):
Sharing a sentence is not in itself a finding about the gene and the disease.
teratoma (3 papers, 2020 to 2025). A non-seminomatous germ cell tumor characterized by the presence of various tissues which correspond to the different germinal layers (endoderm, mesoderm, and ectoderm). "Within teratomas, IMP3 expression has been seen in 100% of mature teratoma components and in 96% of all metastatic testicular teratomas." (PMID 39809819, 2025). "IMP3 overexpression has been identified in several malignancies, including nearly 100% of primary and metastatic postpubertal-type testicular mature teratomas." (PMID 40071092, 2025). "With appropriate methodology aided by the use of positive and negative controls, preferably both internal and external, a positive reaction with IMP3 antibodies in any part of a teratoma raises the suspicion of postpubertal-type (malignant) in adults." (PMID 32144540, 2020). "IMP3 expression may aid the distinction between type I and type II teratomas of the postpubertal testis even when GCNIS and 12p status cannot be assessed." (PMID 32144540, 2020).
adenoma (2 papers, 2021). A neoplasm arising from the epithelium. "The IMP3-positive cell rate in the resected specimens was lower in the adenomas and tended to increase with T-stage in the adenocarcinomas." (PMID 34006250, 2021). "The IMP3-positive cell rate in the biopsy specimens was also lower in the adenomas and tended to increase with T-stage in the adenocarcinomas." (PMID 34006250, 2021). "The distribution of IMP3-positive cells was relatively homogeneous within the tumor, regardless of whether the background tissue was adenocarcinoma or adenoma." (PMID 34006250, 2021).
brain tumor (2 papers, 2015 to 2020). "Next we tested whether IMP3 expression was correlated with brain tumor proliferation, assessed by Ki67 antigen expression." (PMID 25695077, 2015).
carcinoma of the esophagus (2 papers, 2020 to 2023). "In advanced oesophageal cancer, IMP3 and other peptides (TTK, LY6K) have been used therapeutically as vaccines in phase II clinical trials." (PMID 37627115, 2023).
cervical intraepithelial neoplasia (2 papers, 2015 to 2025). "CIN, cervical intraepithelial neoplasia; TPX2, xenopus kinesin-like protein 2; IMP3,insulin-like growth factor II messenger RNA (mRNA)-binding protein 3; PD-L1,programmed cell death-1 ligand-1." (PMID 26624896, 2015).
clear cell carcinoma (2 papers, 2023 to 2024). "Immunohistochemistry markers Napsin A+/IMP3+ are sensitive for this clear cell carcinoma subtype, which were positive in our patient." (PMID 39835055, 2024). "They concluded that IMP3 is a highly sensitive marker for both endometrial serous and clear cell carcinomas." (PMID 36740684, 2023). "The positive IMP3 expression (in more than 5% of tumor cells) was most common in mucinous carcinomas (82%) and mucinous borderline tumors (81%), followed by high grade serous (67%) and clear cell carcinomas (67%)." (PMID 36740684, 2023).
clear cell renal cell carcinoma (2 papers, 2010 to 2013). "The expression of IMP3 in tumor cells has been associated with an unfavorable outcome in renal clear-cell carcinoma." (PMID 24137402, 2013). "To do so, we simulate the creation of a TMA with as few as 1 and as many as 10 cores to study tumor expression of B7-H1, B7-H3, survivin, Ki-67, CAIX, and IMP3 in clear cell renal cell carcinoma (ccRCC)." (PMID 20609235, 2010).
colorectal adenocarcinoma (2 papers, 2013 to 2024). The most common type of colorectal carcinoma. "The aim of the present study was to detect the expression of the IMP3 protein in colorectal adenocarcinoma (CRA) and to identify a correlation with the clinicopathological features of the disease." (PMID 24137402, 2013). "Patients exhibiting high-stage colorectal adenocarcinoma (CRA) and diffuse IMP3 expression exhibited significantly poorer survival rates (p < 0.0001) compared to those without diffuse IMP3 expression (p = 0.0038)." (PMID 39328205, 2024). "Furthermore, multivariate analysis identified diffuse IMP3 expression, serosal invasion, lymph node ratio (LNR), tumor stage, and adjuvant chemotherapy as independent prognostic factors in colorectal adenocarcinoma (CRA)." (PMID 39328205, 2024).
dysplasia (2 papers, 2021 to 2024). A usually neoplastic transformation of the cell, associated with altered architectural tissue patterns. "Over half (56.3%) of the low-grade dysplasia and all the high-grade dysplasia cases showed IMP3 positivity." (PMID 39334193, 2024). "IMP3 expression was analyzed in patients with malignant (laryngeal squamous cell carcinoma), semi-malignant (dysplasia) and benign (nodules, polyps) laryngeal lesions and correlated with clinical characteristics." (PMID 34503117, 2021). "Importantly, IMP3 expression was significantly higher solely in invasive (LSCC) but almost unchanged in noninvasive cases, including benign lesions and patients with dysplasia as well." (PMID 34503117, 2021).
endometrial carcinoma (2 papers, 2023 to 2024). A malignant tumor arising from the epithelium that lines the cavity of the uterine body. "In contrast to previous research, our study demonstrated an association between IMP3 expression and metastasis and advanced staging in endometrial cancer." (PMID 39176196, 2024). "Overall, our results suggest that IMP3 may be a useful biomarker for identifying high-risk subtypes of endometrial cancer and predicting clinical outcomes." (PMID 39176196, 2024). "Our findings indicated significant IMP3 expression in patients with endometrial cancer, consistent with previous literature reporting higher IMP3 expression in several malignant neoplasms." (PMID 39176196, 2024).
gallbladder carcinoma (2 papers, 2017 to 2024). "IMP3 expression in gallbladder carcinomas and dysplasia has shown contrasting findings." (PMID 39334193, 2024).
Hodgkins lymphoma (2 papers, 2022). A heterogeneous group of malignant lymphoid neoplasms of B-cell origin characterized histologically by the presence of Hodgkin and Reed-Sternberg (HRS) cells in the vast majority of cases. "Insulin-like growth factor II mRNA-binding protein 3 (IMP3) is a recently proposed diagnostic marker for Hodgkin’s lymphoma." (PMID 36577979, 2022). "IMP3 was suggested as a diagnostic marker in differentiating Hodgkin lymphoma subtypes, including NLPHL from LBCL." (PMID 36577979, 2022). "Therefore, IMP3 protein was also suggested as a complementary diagnostic marker in Hodgkin’s lymphoma and also differentiating Hodgkin’s lymphoma from LBCL." (PMID 36577979, 2022). "High tissue expression of IMP3 protein was reported in 98.8% of patients with classic and other types of Hodgkin’s lymphoma." (PMID 36577979, 2022). "Furthermore, the mechanistic role of IMP3 in initiation and development of Hodgkin’s lymphoma and its potency to be used as a prognostic or therapeutic marker needs to be investigated." (PMID 36577979, 2022).
keratoacanthoma (2 papers, 2022 to 2023). A dome-shaped, rapidly growing skin lesion composed of well differentiated squamous cells. "Furthermore, it is possible to differentiate between cSCC and keratoacanthoma with the marker IMP3." (PMID 37627115, 2023). "This study also found that while keratoacanthomas (tumors of low malignant potential) did not express appreciable levels of IMP3, IMP3 expression was detected in 19 of 33 cSCC samples." (PMID 35892887, 2022).
liver cancer (2 papers, 2021 to 2025). An epithelial or non-epithelial malignant neoplasm that arises from the liver. "IMP3 is also required in the context of the LIN28B overexpression that drives liver cancer in murine models." (PMID 34154626, 2021).
mesenchymal neoplasms (2 papers, 2015 to 2023). "After exclusion of reactive processes, carcinomas, and mesenchymal neoplasms, additional EMA, desmin, IMP‐3, and thrombomodulin positivity can be observed in the majority of cases, alongside with BAP1 loss." (PMID 36808895, 2023).
metastatic disease (2 papers, 2015 to 2021). "The role of IMP3 in tumor cell proliferation and invasion is further supported by the fact that its expression is associated with an aggressive phenotype with increased risk of progression to metastatic disease in localized renal cell cancers with clear cell and non-clear cell histology." (PMID 25688268, 2015).
neuroendocrine carcinoma (2 papers, 2015 to 2021). A malignant neuroendocrine neoplasm composed of cells containing secretory granules that stain positive for NSE and chromogranin. "One grade 2 NET, one neuroendocrine carcinoma (NEC), and one MiNEN case showed IMP3-positive expression, whereas the other five NET cases showed IMP3-negative expression." (PMID 34446759, 2021).
oral squamous cell carcinoma (2 papers, 2015 to 2024). "Meanwhile, methylation sequencing results showed that the high expression of IMP3 in oral squamous cell carcinoma was probably related to CpG island methylation modification." (PMID 38271139, 2024).
rectal cancer (2 papers, 2021 to 2023). A primary or metastatic malignant neoplasm that affects the rectum. "In the group of patients that died of rectal cancer there were 3.9 times more IMP3 positive expression than in the group of survived patients (p < 0.001)." (PMID 34035433, 2021). "The analysis of IMP3 expression by immunohistochemistry pointed IMP3 as an independent prognostic factor of clinical stage II rectal cancer." (PMID 34035433, 2021). "To date, there are a small number of papers analyzing the expression of IMP3 in the whole tissue samples of rectal cancer." (PMID 34035433, 2021). "Immunohistochemical level of IMP3-protein in patients with rectal cancer in clinical stage II, were correlated with sociodemographic, pathohistological and clinical indicators and duration of overall-survival and progression-free-survival." (PMID 34035433, 2021). "In this study, IMP3 expression was analyzed for the first time in tumor samples of a selected population with rectal cancer in clinical stage II." (PMID 34035433, 2021). "The analysis of IMP3 immunohistochemical expression pointed IMP3 as an independent prognostic factor of clinical stage II rectal cancer." (PMID 34035433, 2021). "Therefore, our research, which expand existing knowledge on the role of IMP3 protein in rectal cancer, can contribute to the understanding of the IMP3 cellular pathway involved in invasion and metastasis in the rectum carcinomas." (PMID 34035433, 2021). "Therefore, in this study, the expression of IMP3 protein in tissue samples of patients with rectal carcinomas was investigated in this prognostically and therapeutically the least defined clinical stage II." (PMID 34035433, 2021). "Patients with rectal cancer and high IMP3-protein level will have a shorter overall survival relative to patients without or with low levels of IMP3." (PMID 34035433, 2021).
renal carcinoma (2 papers, 2016 to 2021). A carcinoma arising from the epithelium of the renal parenchyma or the renal pelvis. "They showed that 2-3 cores appeared to be adequate for assessing the status of B7-H3, Ki-67, CAIX, and IMP3 expression in renal cancer patients, whereas as many as 10 cores were insufficient for assessing B7-H1." (PMID 26863572, 2016).
serous endometrial adenocarcinoma (2 papers, 2022 to 2024). "There is a higher expression of IMP3 in intensity and extension in cases of serous endometrial adenocarcinoma (intensity: p = 0.044; extension: p <0.001)." (PMID 39176196, 2024).
testicular teratoma (2 papers, 2020 to 2025). "The aim of this study was to assess histological characteristics, IMP3 expression and the presence of 12p abnormalities of pure testicular teratomas." (PMID 32144540, 2020). "The aim of the present study was to determine the characteristics of prepubertal-type and postpubertal-type pure testicular teratomas regarding histological composition, IMP3 expression, and the presence of 12p abnormalities." (PMID 32144540, 2020).
urothelial carcinoma (2 papers, 2016 to 2019). A malignant neoplasm derived from the transitional epithelium of the urinary tract (urinary bladder, ureter, urethra, or renal pelvis). "The expression intensity of IMP3 in muscle-invasive samples was significantly higher than that in non-muscle-invasive urothelial carcinoma specimens (P = .008)." (PMID 31277094, 2019). "In our study, we determined the expression of IMP3 in 203 urothelial carcinomas (183 non-muscle-invasive and 20 muscle-invasive) and 20 benign tissues adjacent to cancer tissue by IHC." (PMID 31277094, 2019). "IMP3 expression was significantly related with advanced tumor stage (P < .001), advanced tumor grade (P = .004), and tumor recurrence (P < .001) in non-muscle-invasive urothelial carcinomas." (PMID 31277094, 2019).
acral lentiginous melanoma (1 paper, 2016). A form of melanoma occurring most often on the plantar, palmar, subungual, and periungual skin. "However, the expression of IMP-3 has not been investigated in acral lentiginous melanoma (ALM)." (PMID 26796627, 2016).
acute liver failure (1 paper, 2022). Rapid deterioration of liver function causing encephalopathy and coagulopathy. "In addition, a study for acute liver failure has reported that in healthy mouse liver, only a small population of cells expressing IMP3 were identified by immunohistochemistry." (PMID 35315195, 2022).
adenoid cystic carcinoma (1 paper, 2020). A malignant tumor arising from the epithelial cells. "In conclusion, IMP3 has higher efficacy in diagnosis of mucoepidermoid carcinoma than adenoid cystic carcinoma, especially in problematic conflicts like suspicious cases or poor tissue sampling, and demonstrated the role of this protein in diagnosing salivary gland tumors." (PMID 32692399, 2020).
anaplastic astrocytoma (1 paper, 2015). "GBMs expressed higher Ki67 levels compared to anaplastic astrocytomas (P = 0.0014), but IMP3 expression was not correlated with the proliferation index in GBM and grade III tumors." (PMID 25695077, 2015).
anaplastic gliomas (1 paper, 2015). "With regard to anaplastic gliomas (grade III), 84% of IMP3-positive cases showed astrocytic differentiation and we could speculate that IMP3 expression is more likely associated with astrocytic lineage." (PMID 25695077, 2015).
autoimmune pancreatitis (1 paper, 2022). "Another study utilized IMP3, Maspin, S100P, and von-Hippel-Lindau gene protein (pVHL) for comparison between autoimmune pancreatitis (AIP), PDAC, and normal pancreas specimens." (PMID 35565450, 2022).
Azoospermia (1 paper, 2023). Absence of any measurable level of sperm,whereby spermatozoa cannot be observed even after centrifugation of the semen pellet. "We randomly chose five structures of other nucleic acid-bound RRM1 motifs, including human RBM45 (PDB ID: 7CSZ), DAZL (azoospermia (DAZ)-like) (PDB ID: 2XS5), hnRNP A1 (PDB ID: 5MPG), U2AF2 (PDB ID: 6XLW), and IMP3 (PDB ID: 6GX6), for comparison." (PMID 37253421, 2023).
benign prostate hyperplasia (1 paper, 2010). "In samples from non neoplastic prostate tissue and from benign prostate hyperplasia, no remarkable IMP3 protein expression was found (n = 31, 100% negative)." (PMID 20591150, 2010).
cartilaginous tumors (1 paper, 2024). "Several oncogenic signaling pathways have been implicated in the progression of cartilaginous tumors, such as those related to cell migration (IMP3) and cell cycle (CDK4, MDM2, and β-catenin), which should be better elucidated." (PMID 39368400, 2024).
cholangiocarcinoma (1 paper, 2024). A carcinoma that arises from the intrahepatic biliary tree (intrahepatic cholangiocarcinoma) or from the junction, or adjacent to the junction, of the right and left hepatic ducts (hilar cholangiocarcinoma). "GBC expressed IMP3 most strongly at 81.6%, whereas intra- and extra-hepatic cholangiocarcinoma showed IMP3 positivity rates of 36.8% and 50%, respectively." (PMID 39334193, 2024).
chondrosarcoma (1 paper, 2024). A malignant cartilaginous matrix-producing mesenchymal neoplasm arising from the bone and soft tissue. "The positivity of IMP3, CDK4, MDM2 and β-catenin antibodies was directly proportional to the increase of histological grade in Chondrosarcoma." (PMID 39368400, 2024). "The significant immunoexpression of IMP3, CDK4 and MDM2 in metastatic Chondrosarcoma and the lower survival in those with positivity for MDM2 suggest a possible association of these proteins with tumor aggressiveness." (PMID 39368400, 2024).
colorectal tumor (1 paper, 2021). "Data showed that IMP3 was significantly upregulated in colorectal tumor tissues (n = 647) when compared with normal epithelial tissues (n = 51, p < 0.05)." (PMID 34154626, 2021).
endometrial tumors (1 paper, 2024). "IMP3 expression was also significant in extent (p=0.002) in endometrial tumors compared with controls." (PMID 39176196, 2024).
endometriosis (1 paper, 2015). The growth of functional endometrial tissue in anatomic sites outside the uterine body. "Regarding preinvasive lesions, we recently demonstrated that IMP3 can help in discriminating endometriotic cysts with reactive atypia from cysts lined by preneoplastic atypical endometriosis." (PMID 25695077, 2015).
giant cell tumor (1 paper, 2024). A benign, intermediate, or malignant tumor that arises from the bone or soft tissue. "IMP3 and IGF2 might be potential biomarkers for GCT of the spine in regulating the angiogenesis of giant cell tumor of bone and predicting patients’ prognosis." (PMID 39795567, 2024).
head and neck cancer (1 paper, 2022). A primary or metastatic malignant neoplasm affecting the head and neck. "However, OS was significantly longer in patients with advanced head and neck cancer treated with LY6K, CDCA1, and IMP3 peptides who were A24(+) compared with those who were A24(–); median survival time was 4.9 versus 3.5 months; p < 0.05)." (PMID 38993370, 2022).
laryngeal carcinoma (1 paper, 2021). Carcinoma that arises from the laryngeal epithelium. "In laryngeal cancer patients, higher IMP3 expression was associated with positive neck nodes and worse disease-specific survival." (PMID 34503117, 2021).
lung squamous cell carcinoma (1 paper, 2015). "In our previous study, it was shown that IMP3 expression predicts a poor prognosis in patients with lung squamous cell carcinoma." (PMID 25789070, 2015).
malignant smooth muscle tumors (1 paper, 2024). "Therefore, to distinguish between benign and malignant smooth muscle tumors, IMP3 staining can be a helpful adjunct." (PMID 38818470, 2024). "Additionally, IMP3 expression in the uterus can be utilized as a positive biomarker to raise the degree of confidence in the final diagnosis of malignant smooth muscle tumors." (PMID 38818470, 2024).
metastatic melanoma (1 paper, 2016). A melanoma that has spread from its primary site to another anatomic site. "In our previous study, IMP-3 expression was much stronger in advanced-stage/metastatic melanomas and correlated with poor overall survival (OS)." (PMID 26796627, 2016).
mucinous ovarian adenocarcinomas (1 paper, 2024). "IMP3 has been observed to vary significantly between metastatic and primary mucinous ovarian adenocarcinomas, with its expression correlating with tumor aggressiveness." (PMID 39040449, 2024).
neuroendocrine tumors (1 paper, 2023). "Another study demonstrated that inhibition of IMP3 expression in cell lines of neuroendocrine tumors leads to downregulation of EGFR and Ki-67, proteins associated with cell proliferation, and these authors suggest IMP3 as a promising therapeutic target." (PMID 36740684, 2023).
neuroendocrine tumors of the lung (1 paper, 2021). "On the other hand, other studies have introduced IMP3 as a prognostic biomarker for certain malignant tumors such as those found in the bile duct, neuroendocrine tumors of the lung, and peritoneal mesothelioma." (PMID 33680717, 2021).
oral cancer (1 paper, 2023). "A similar correlation of IMP3 expression and the risk for LNMs was found in literature for oral cancer." (PMID 37627115, 2023).